EGFR (epidermal growth factor receptor)
Diseases named in the same sentence as EGFR in open-access papers (continued):
Sharing a sentence is not in itself a finding about the gene and the disease.
prostate carcinoma (continued). "Conversely, a transient upregulation of EGFR was shown in the prostate carcinoma cell line DU-145 after treatment with the HDACi SN30028, which inhibits not only class I HDACs, but also the class IIb representative HDAC6." (PMID 39864337, 2025). "The identification of EGFR as an interaction partner of B7-H3 in prostate cancer cells reveals a potential direct link between B7-H3 and tumor-promoting signaling pathways." (PMID 40004194, 2025). "The relationship between INSM1, EGFR, and cell cycle has been confirmed to be a key factor in NE transformation of prostate cancer." (PMID 40437627, 2025). "PTX3 is upregulated in prostate cancers at both mRNA and protein levels, and is positively correlated with expression of ERα and EGFR." (PMID 41479916, 2025). "In prostate cancer, IGFBP3 causes resistance to poly(adenosine diphosphate-ribose) polymerase (PARP) inhibitors through interaction with DNA-PKcs and EGFR." (PMID 41199784, 2025). "Epidermal growth factor receptor (EGFR) is expressed on 41% of newly diagnosed prostate cancers, 76% of CRPCs, and 100% of metastatic prostate cancers." (PMID 39904797, 2025). "TDEVs contain tumor-specific molecular markers on their surfaces and within their structure, such as PSMA and STEAP1 in prostate cancer; EGFR and HER2 in bladder cancer; and CAIX in kidney cancer." (PMID 41459253, 2025). "Using this approach, we identified CD45 as a potential B7-H3 interaction partner on Raji B cells and epidermal growth factor receptor (EGFR) as a potential interaction partner on prostate cancer cell line PC3." (PMID 40004194, 2025). "Stable expression of EGFR protein levels effectively promotes malignant progression of prostate cancer by activating multiple signaling pathways." (PMID 40672756, 2025). "EGFR is a key protein in the cancer pathway, prostate cancer pathway (Prostate cancer) and PI3K-Akt signaling pathway." (PMID 40230723, 2025). "For example, CMTM5-v1 inhibits cell growth and migration by downregulating EGFR signaling in prostate cancer." (PMID 40179060, 2025). "The APMAP/EGFR axis enhances cholesterol-induced EMT in prostatic carcinoma, and APMAP promotes metastasis of cervical cancer by activating the Wnt/β-catenin pathway." (PMID 40821803, 2025). "While NRG1β induces significant phosphorylation of EGFR, ASPN activation of EGFR is limited, suggesting that ASPN-induced ErbB signaling in prostate cancer is primarily through HER2 and HER3." (PMID 40857406, 2025). "At the same time, WFDC2 also inhibits epithelial-mesenchymal transition in prostate cancer through inactivating EGFR signaling." (PMID 39296934, 2024). "High frequencies of CNAs were observed in PIK3CA, FGFR1, and EGFR in breast, ovary, pancreas, and prostate cancer samples." (PMID 38674331, 2024). "This study aimed to evaluate the effects of the GHRH-R antagonist MIA-690, in combination with the EGFR inhibitor Gefitinib, on cell viability, adhesion, gelatinolytic activity, and the cell cycle in advanced prostate cancer PC-3 cells." (PMID 39456984, 2024). "SPINK1 has been found to stimulate cell proliferation and contributes to prostate cancer cell plasticity through its interaction with the epidermal growth factor receptor." (PMID 38173042, 2024). "A Chip assay generated data revelled the binding of EGF/EGFR complex to the promoter of CYP27B1 in PZ‐HPV7 cells which leads to prostate cancer development." (PMID 39434198, 2024). "In the cellular pathway, signal transduction adapter family member-2 (STAP-2) promotes tumorigenesis in prostate cancer cells by upregulating the EGF receptor (EGFR) signaling pathway." (PMID 39130630, 2024). "FABP5 seems to be connected with the epidermal growth factor receptor (EGFR), which regulates endothelial cell proliferation, promoting the growth of tumor cells in breast and prostate cancer." (PMID 38777142, 2024). "The epidermal growth factor receptor (EGFR) is highly expressed in breast, head and neck, non-small cell lung, and prostate cancers." (PMID 39861688, 2024).
prostate carcinoma (continued). "The manuscript discusses how lncRNAs like HULC and RHPN1-AS1 influence autophagy and therapy resistance in prostate cancer by interacting with pathways like mTOR and EGFR signaling." (PMID 39512820, 2024). "STAP-2 increases EGFR phosphorylation in response to EGF and upregulates EGFR signaling in the prostate cancer cell line DU145." (PMID 38461189, 2024). "WFDC2 inhibits EGFR activation by binding to its extracellular domain, thus inhibiting prostate cancer metastasis." (PMID 39296934, 2024). "This is consistent with the previous finding that HE4 binds to the extracellular domain of EGFR in prostate cancer." (PMID 38827327, 2024). "Our collective research has also shown that CFF-1 exerts potent anti-tumor immunity, effectively hindering tumor growth and metastasis in prostate cancer via the EGFR/JAK1/STAT3 pathway, subsequently inhibiting PD-1/PD-L1 checkpoint signaling." (PMID 38484140, 2024). "For example, lncRNA HULC and RHPN1-AS1 have been shown to regulate autophagy and influence therapy resistance in prostate cancer through their interactions with mTOR and EGFR signaling, respectively." (PMID 39512820, 2024). "Overexpression of miR-152 in PC-3 and DU145 cells effectively suppressed the invasive and migratory abilities of prostate cancer cells by targeting TGFα, a key player in EGFR signaling." (PMID 39606232, 2024). "An additional study reported that UBTD1 can interact with another E3 ligase, RNF26, to upregulate the ubiquitination of autophagy-related protein p62 and enhance the lysosomal degradation of EGFR in prostate cancer cells." (PMID 39003255, 2024). "EGFR is of significance to the progression of prostate cancer, exhibiting high expression levels in certain prostate cancer cells." (PMID 39771106, 2024). "GATA2 is a critical pioneer TF for AR, trans-activated IGF2 to mediate taxane resistance in prostate cancer or promote chemoresistance in gastric cancer via the EGFR signalling pathway." (PMID 38126976, 2023). "A number of studies in prostate cancer have demonstrated that NDRG1 associates with androgen receptors and inhibits a range of critical signalling pathways, including EGFR, HER2, HER3, PI3K, and STAT3." (PMID 36765657, 2023). "EGFR signaling pathways promote proliferation, survival, invasiveness and metastasis of prostate cancer cells 10-12 and EGFR expression correlates with grading, recurrence, poorer metastasis-free survival and therapeutic resistance of prostate cancer 13-16." (PMID 37859824, 2023). "It was possible to evidence the high extent of EGFR recognition of DU145 prostate cancer cells by the immunoliposome." (PMID 36986777, 2023). "Specific tyrosine kinase pathways in the development of prostatic cancer, including the activation of EGFR, ephrin type-A receptor 2, and JAK2, have been identified in a mouse model." (PMID 38136890, 2023). "Epidermal growth factor receptor (EGFR), a known marker of dissemination of prostate cancer to bones, was detected with 19 biotinylation sites." (PMID 38053024, 2023). "Cell cycle analysis, apoptotic induction, molecular docking, dynamics, and MM-GBSA studies confirmed the plausible mechanism(s) of compound 9f as a potent EGFR/HER2 dual inhibitor with an effective antiproliferative action against prostate carcinoma." (PMID 37096560, 2023). "In the present study, we generated the new targeted toxin EGF-PE24mutΔREDLK binding to the epidermal growth factor receptor (EGFR) on the surface of prostate cancer cells." (PMID 37859824, 2023). "CMTM5-v1 inhibits cell proliferation and migration by downregulating the EGFR signaling pathway in prostate cancer." (PMID 37654657, 2023). "The GABA or GABAB agonist baclofen has been demonstrated to promote Epidermal growth factor receptor (EGFR) transactivation, which has been connected to the propensity of prostate cancer cells to invade." (PMID 37051193, 2023).
prostate carcinoma (continued). "Regarding prostate cancer, the crosstalk between AR and EGFR signaling has been discussed from different viewpoints depending on the cell lines and culture conditions." (PMID 37463954, 2023). "There was also a concurrent increase in the expression of epidermal growth factor receptor (EGFR), a key receptor in carcinogenesis, with clathrin in prostate cancer tissue, indicating recycling of EGFR through clathrin-mediated endocytosis (CME)." (PMID 36869937, 2023). "By administering gefitinib together with hormone-depleted therapy for prostate cancer, it is expected that the switch to EGFR signaling via 3-O-sulfated HS will be suppressed and the development of CRPC will be prevented." (PMID 37463954, 2023). "We address formulation development, physicochemical characterization, liposomal functionalization with cetuximab and finally, cytotoxicity and cellular uptake on prostate cancer cells with low and high EGFR expression." (PMID 36986777, 2023). "Recently, a similar approach has been proposed for prostate cancer, and it has been demonstrated that, in prostate cellular models, celecoxib reduces cell growth, induces apoptosis, and promotes EGFR degradation." (PMID 37190301, 2023). "The reduced activation of miR-146a was described in castration-resistant prostate cancer, where it controls the expression of EGFR and MMP2 in prostate cancer tissue." (PMID 37108432, 2023). "An increase in EGFR in MCSs was measured after a 24 h RPM exposure of PC-3 prostate cancer cells, indicating its early involvement in MCS formation." (PMID 36674696, 2023). "The Akt downstream signaling pathway has been implicated in EGFR (Epidermal Growth Factor Receptor) signaling and cell motility in PC3 and DU145 cells for prostate cancer progression." (PMID 36839985, 2023). "This protein, a co-receptor for various growth factors, is known to promote prostate cancer progression via modulating EGFR-dependent AKT pathway activation." (PMID 38053024, 2023). "Significant prevalence differences compared to TCGA were identified, including a high prevalence of EGFR in lung (P = 0.001); RB1 in breast (P = 0.0002); and multiple mutations in prostate cancer." (PMID 37702806, 2023). "Recently, we generated targeted toxins binding to the epidermal growth factor receptor (EGFR) for the treatment of prostate cancer." (PMID 37859824, 2023). "Although all prostate cancer cell lines we tested to have comparable EGFR expression 9, we determined LNCaP cells to be most sensitive to combination treatment." (PMID 37859824, 2023). "In prostate cancer, it downregulates epidermal growth factor receptor (EGFR) signaling, leading to cell cycle arrest and reduced expression of tumor growth factor (TGF-α)." (PMID 37915411, 2023). "STAP-2 enhances signaling via EGFR through its protein stabilization, leading to higher tumorigenesis in prostate cancer cells." (PMID 36010693, 2022). "EGFR signaling promotes prostate cancer cell invasiveness and metastasis by inducing epithelial-to-mesenchymal transition (EMT), resistance to chemotherapy and, ultimately, disease relapse." (PMID 35954439, 2022). "Patients with positive family history for prostate cancer showed high levels of EGFR, TG, TC, LDL, alkaline phosphatase (ALP), but low AKR1C4, SLDLRP1, CAV1 and ABCA-1 levels." (PMID 36480560, 2022). "It was reported that miR-1231 downregulation suppresses prostate cancer cell proliferation, migration, and invasion by targeting EGFR." (PMID 36230873, 2022). "LncRNA LOXL1-AS1 is capable of promoting epidermal growth factor receptor (EGFR) in prostate cancer via miRNA-3et-7a-5p down-regulation to mediate DOX resistance." (PMID 35773731, 2022). "Immunoliposomes targeted with epidermal growth factor receptor (EGFR) and loaded with Dtx have been tested against prostate cancer." (PMID 35625921, 2022).
prostate carcinoma (continued). "A recent study revealed that the combined protein expression patterns of EGFR, ERBB2, and ERBB3 were associated with a higher risk of progression and mortality in prostate cancer." (PMID 36095024, 2022). "PSMA has, however, been shown to allow the activation of EGFR through the assembly of a multi-protein signaling complex in prostate cancer cell lines." (PMID 35086953, 2022). "ADAM17 targets MMP2 and MMP-9 via EGFR-MEK-ERK pathway activation to promote prostate cancer cell invasion." (PMID 36172139, 2022). "The EGFR/ERBB4, MET and IGF-1R families of growth factor receptor have been implicated in prostate cancer." (PMID 35954439, 2022). "In a SPINK1-positive prostate cancer xenografted mice study, monoclonal EGFR antibody was administered and showed decrease in tumor burden, indicating interaction with EGFR." (PMID 36053457, 2022). "For KEGG pathway analysis, both of the targets were particularly enriched in proteoglycans in cancer, microRNAs in cancer, prostate cancer, EGFR tyrosine kinase inhibitor resistance, and endocrine resistance (P < 0.05)." (PMID 35356765, 2022). "It was shown that nuclear EGFR directly and transcriptionally regulates miR-1 in prostate cancer cells, indicating that miR-1 is one of the targets of EGFR." (PMID 36471329, 2022). "Similar to PD-1/PD-L1, development of optimized peptides to inhibit the interactions between STAP-2 and EGFR is likely to have applications in the treatment of EGFR-related malignancies such as lung and prostate cancers." (PMID 36410436, 2022). "The cytotoxicity assessments were done on DU145 (with high expression of EGFR) and PC3 (with low EGFR expression) prostate cancer cell lines." (PMID 36559202, 2022). "After topological enrichment, the most connected upregulated genes MYC, CDK1, CCNB1 etc. and the most connected downregulated genes EGFR, VEGFA, STAT3 etc. were categorized according to their highest degree count associated with prostate cancer." (PMID 35456461, 2022). "FOXM1 and CDK1 from the KEGG Senescence pathway and EGFR from the Prostate Cancer Pathway are also involved in the DNA repair process." (PMID 35205253, 2022). "Another study found SCIN was highly expressed in prostate cancer and promoted prostate cancer cell proliferation by the EGFR and MEK/ERK singling pathway." (PMID 36291348, 2022). "Another biological mechanism of STAP-2 in prostate cancer cells is to inhibit the CBL-enhanced ubiquitination of EGFR and to restore EGFR." (PMID 36010693, 2022). "This study suggests a tumor-suppressor role for DHRS7 by modulating EGFR expression in prostate cancer." (PMID 35804847, 2022). "SOX2 plays a critical role in EGFR-mediated self-renewal of human prostate cancer stem–like cells derived from DU145 cells." (PMID 34809669, 2021). "The overall reduction in the expression of ARS was found to be related to prostate cancer aggressiveness, due to the association between ARSB and the epidermal growth factor receptor (EGFR), commonly overexpressed when ARSB is reduced." (PMID 33445445, 2021). "We checked for cellular effects of SF5-SAHA by determination of changes in the expression level of the EGFR in DU145 prostate cancer cells." (PMID 34959719, 2021). "Curcumin was also useful against prostate cancer as it interfered with nuclear factor κ (NFκB), epidermal growth factor receptor (EGFR), and mitogen-activated protein kinase (MAPK)." (PMID 33920079, 2021).
prostate carcinoma (continued). "(EGFR and ALK in NSCLC, BRCA1 and BRCA2 in breast and ovarian cancer and homologous recombinant deficiency in prostate cancer)." (PMID 35047063, 2021). "They showed that inhibition of SGLT1 by its inhibitor (florinsine) sensitized prostate cancer cells to treatment with an EGFR tyrosine kinase inhibitor (gefitinib and erlotinib)." (PMID 33921222, 2021). "EGFR signaling plays an important role in the transition from androgen dependence to castration-resistant state in prostate cancer (PCa)." (PMID 34804913, 2021). "In comparison, other studies observed in prostate cancer that CBR1 expression was positively correlated with the epidermal growth factor receptor (EGFR) (rs = 0.316, p < 0.001)." (PMID 34575629, 2021). "We also checked for cellular effects of the novel compounds by determination of changes in the protein level of the EGFR in DU145 prostate cancer cells." (PMID 34445133, 2021). "In prostate cancer, some have shown that AR and EGFR proteins are inversely correlated, while others have shown a positive correlation." (PMID 34681618, 2021). "AA-prostate cancer patients have also been shown to express higher levels of EGFR compared to CA prostate cancer patients." (PMID 33996789, 2021). "Here, our IHC data revealed a low-level expression of CXCL14 and a high EGFR expression in prostate cancer tissues." (PMID 34696665, 2021). "In prostate cancer, EGFR was found to mediate SPINK1′s biological function when triggering the epithelial–mesenchymal transition." (PMID 33916984, 2021). "An EGFR-targeted nanoparticle delivery system containing curcumin (0.58 μM) and docetaxel (0.058 μM) was developed to induce EGFR-mediated endocytosis in prostate cancer cells." (PMID 34299604, 2021). "The loss of radiosensitivity and its implication on presentation and activation of the EGFR during progression should lead to new treatment strategies for prostate cancer using targeted therapies." (PMID 34321039, 2021). "Next, we examined the association of EGFR and YB-1 as well as CXCL14 expression with clinical and pathological characteristics in human prostate cancer tissues using IHC." (PMID 34696665, 2021). "Our IHC study illustrated that YB-1 and EGFR are significantly expressed in prostate cancer tissues with a high Gleason score, while CXCL14 was lowly expressed." (PMID 34696665, 2021). "It has been proven that the lncRNA FAM66C activates the EGFR-ERK pathway to promote cell proliferation in prostate cancer." (PMID 34490250, 2021). "Many studies have confirmed that EGF/EGFR signaling is one important growth factor signaling involved in the regulation, proliferation, and survival of prostate cancer." (PMID 34069970, 2021). "In the present study, we discovered a reverse correlation of exosomal miR‐3934‐5p expression levels with EGFR signaling as well as prostate cancer cell metastasis, which was regulated by EWI‐2." (PMID 33605506, 2021). "We observed high expression levels of EGFR in human prostate cancer tissues and a low or minimal EGFR expression had the ability to prolong overall survival." (PMID 34696665, 2021). "The knockdown of GBP1 inhibits xenograft growth and the protein expression level of EGFR is decreased in GBP1-knockout xenograft tumors in prostate cancer." (PMID 34439200, 2021). "Inhibition of EGFR with cetuximab shows significantly improved PFS in prostate cancer patients with an overexpression of EGFR and persistent activity of PTEN." (PMID 33224867, 2020). "In prostate cancer, EGFR signaling pathway induces SPINK1 trypsin inhibitor to promote EMT and overexpression of SPINK1 represents its aggressive form." (PMID 33298014, 2020).